CCR6 (C-C motif chemokine receptor 6)
Diseases named in the same sentence as CCR6 in open-access papers (continued):
Sharing a sentence is not in itself a finding about the gene and the disease.
colitis (21 papers, 2011 to 2025). Inflammation of the colon. "Here, we further investigate how these Th17-like Tregs and the chemokine receptor CCR6 affect the immunoregulation of Blimp-1 deficiency-mediated colitis in diabetes-prone NOD mice." (PMID 41197380, 2025). "CCR6-deficient mice expressing spontaneous colitis displayed increased resistance to colonic inflammation reducing colitis severity in the mouse model." (PMID 37092451, 2023). "Concomitantly, expression of Il6, Tnf and Il1β were reduced in colitis colons of CCR-6-deficient mice." (PMID 29695802, 2018). "In a third widely used classical model of colitis induced by T cell transfer, naïve T cells from CCR6−/− mice transferred into Rag2−/−mice caused a very severe colitis compared to CCR6+/+ transferred T cells." (PMID 23874340, 2013). "Importantly, CCL20 is known to recruit pathogenic lymphocytes by acting on its receptor CCR6 in colitis and molecules targeting the CCL20/CCR6 axis are already in clinical development." (PMID 40342995, 2025). "To directly examine whether the CCL-20/CCR-6 axis is necessary for lymphocyte recruitment during colitis, we investigated CCR-6-deficient mice (Ccr6KO) in our CAC model." (PMID 29695802, 2018). "During the colitis phase, CCR-6-deficient mice exhibited reduced weight loss." (PMID 29695802, 2018). "Hence, the substantially reduced Ccl20 expression in colons of Il6rαKO mice is a consequence of collapsed M2-type polarisation of IL-6Rα-deficient macrophages in CAC, thereby compromising CCR-6-expressing lymphocyte recruitment in colitis to promote tumourigenesis." (PMID 29695802, 2018). "In contrast, the TNBS- and DSS-induced colitis models—which feature rapid onset and early chemokine-driven immune cell recruitment—appear more responsive to CCR6-targeted intervention." (PMID 41011197, 2025). "Here, the DSS-induced colitis mice showed a remarkable imbalance with a significant increase in CD4+CCR6+ Th17 cells and a significant decrease in CD4+Foxp3+ Treg cells in the mesenteric lymph nodes (MLNs)." (PMID 38202824, 2024). "Until now, little has been known about the function of CCR6+ γδ T cells in vivo, although these cells have also been detected in a colitis model." (PMID 37475963, 2023). "Collectively, these experiments reveal a crucial role for the recruitment of CCR-6-expressing lymphocytes into the colon during the colitis phase to promote CAC." (PMID 29695802, 2018). "Collectively, these analyses reveal that during colitis CCL-20-recruited CCR-6+ B cells promote CAC." (PMID 29695802, 2018). "A prominent CCR-6-expressing lymphocyte population comprises mature B cells and B cells exert macrophage-polarising functions in colitis." (PMID 29695802, 2018). "Although most γδ T cells express CCR-6 during colitis in untreated mice, a proportion of γδ T cells in antibody-treated mice were negative for CCR-6 expression." (PMID 29695802, 2018). "This indicates that the protection from colitis is offered by a novel colon-homing, IL-10-producing CCR6+ regulatory T cell population." (PMID 23874340, 2013). "In the dextran sulfate sodium (DSS) model of colitis, CCR6−/− mice developed less severe colitis compared to WT mice, while in the 2,4,6-trinitrobenzene sulfonic acid (TNBS)-induced model, the clinical picture of colitis was stronger." (PMID 23874340, 2013). "Critically, the colitis mice also exhibited an abnormal imbalance of mTh17/mTreg cells with higher frequencies of CD4+CCR7+CCR6+ cmTh17 and CD4+CCR7−CCR6+ emTh17 cells and lower frequencies of CD4+CCR7+Foxp3+ cmTreg and CD4+CCR7−Foxp3+ emTreg cells in the MLNs." (PMID 38202824, 2024). "This is of critical importance as a pathogenic role of ILC3 has been shown in colitis mouse models with H. hepaticus and anti-CD40 antibody driven colitis and even IBD patients and CCR6+ ILC3 have been linked to enhanced airway hyperreactivity in an obesity model." (PMID 34795671, 2021).
colitis (continued). "It is plausible to hypothesize that in our model Hp-promoted colitis in Hh-infected males could be mediated by enhancing the response of a CCR6+ T-bet- Il17-producing subset of ILC3s." (PMID 33255175, 2020). "Therefore, we conclude that CCL-20 released in the colitis phase recruits CCR-6-expressing lymphocytes that promote CAC tumourigenesis." (PMID 29695802, 2018). "Collectively, these experiments suggest that CCL-20 is expressed by M2-type macrophages in colitis and that the inability of IL-6Rα-deficient macrophages to polarise towards M2-type impedes on CCL-20 expression and presumably on recruitment of CCR-6-expressing cells." (PMID 29695802, 2018). "Thus, these analyses demonstrate that CCR-6-expressing cells are recruited during colitis and that CCR-6 deficiency largely protects against colitis." (PMID 29695802, 2018). "However, which CCR-6-expressing lymphocyte population, that is recruited to the colon in colitis promotes CAC, still has to be investigated." (PMID 29695802, 2018). "Furthermore, co-staining with CCR-6 antibody revealed that the majority of B cells and γδ T cells in colitis express CCR-6, whereas only a minority of αβ T cells express the CCR-6 receptor when compared with their total numbers." (PMID 29695802, 2018). "Importantly, in this study, we detected higher CCR6 mRNA expression in DSS-induced colitis BALB/c mice as compared to C57BL/6 mice." (PMID 28584821, 2017). "Importantly, APS reversed the expression changes in the TIGIT molecule on mTh17/mTreg cells in the colitis mice with fewer CD4+CCR6+TIGIT+, CD4+CCR7−CCR6+TIGIT+ and CD4+CCR7−CCR6+TIGIT+ cells and more CD4+Foxp3+TIGIT+, CD4+CCR7−Foxp3+TIGIT+ and CD4+CCR7−Foxp3+TIGIT+ cells." (PMID 38202824, 2024). "In the present study, we also found that the colitis mice presented similar results with lower frequencies of mTreg (CD4+Foxp3+, CD4+CCR7+Foxp3+, CD4+CCR7−Foxp3+) cells and higher mTh17 (CD4+CCR6+, CD4+CCR7+CCR6+, CD4+CCR7−CCR6+) cells." (PMID 38202824, 2024). "Pretreatment with compounds 7b and 13b alleviated the severity of colitis and concomitantly counteracted the increased levels of RORγt, STAT3, CCR6, IL-6, IL-17, IL-23, TNF-α, and PGE2." (PMID 36077306, 2022). "The immunohistochemical evaluation showed that induction of colitis increased the expression of RORγt, STAT3, and CCR6 in the colon tissues compared to the control group (p < 0.01, p < 0.01, p < 0.001, respectively)." (PMID 36077306, 2022). "RT‐PCR and IHC analysis validated that TOE up‐regulated the expression of Adh5, Aldh3a2 and Acox3, but down‐regulated the expression of CCL20, CXCL5, CCR6 and CXCL1 in DSS‐induced colitis." (PMID 31565850, 2019). "In the colitis phase of CAC, IL-6-polarised M2-like macrophages express the chemokine CCL-20 that recruits CCR-6-expressing lymphocytes, further promoting CAC progression." (PMID 29695802, 2018). "Thus, it is tempting to speculate that differential regulation of CCR6 between C57BL/6 and BALB/c mice is responsible for differences in the infiltration of Th17 and Treg to the colon of mice and the associated susceptibility to colitis." (PMID 28584821, 2017). "Future studies to explore this aspect can employ the use of other mouse models to further clarify the relationship between CCR6, TH17 cells, and colitis." (PMID 23874340, 2013). "To date, targeting of chemokine receptors such as CCR2, CCR5, CCR6, CXCR3, CXCR4 and CX3CR1 by gene disruption or antagonistic peptides has been found to protect animals from DSS colitis." (PMID 21283540, 2011). "Overall, T-bet deficiency caused increased NKp46- CCR6- ILC3 and ILC2 cellularity in Rag-sufficient mice, but not at the cost of spontaneous colitis as observed in H. thyphlonius-infected Rag2-/-xTbx21-/- mice." (PMID 33603753, 2020). "To quantify CCR-6+ lymphocyte recruitment in 1.5% AOM/DSS-induced colitis, we examined total cell numbers from non-colitic and colitic control as well as IL-6Rα-deficient colons by FACS." (PMID 29695802, 2018).
colitis (continued). "Notably, APS significantly down-regulated the percentages of Th17 (CD4+CCR6+), cmTh17 (CD4+CCR7+CCR6+) and emTh17 (CD4+CCR7−CCR6+) cells and significantly up-regulated the percentages of cmTreg (CD4+CCR7+Foxp3+) and emTreg (CD4+CCR7−Foxp3+) cells in the mesenteric lymph nodes of the colitis mice." (PMID 38202824, 2024).
inflammatory bowel disease (21 papers, 2009 to 2025). A spectrum of small and large bowel inflammatory diseases of unknown etiology. "Recently, CCR6 has been implicated in inflammatory bowel disease (IBD) by genome wide association studies which showed an association between SNPs in the genomic region of the CCR6 gene and the inflammation." (PMID 23874340, 2013). "A human study of inflammatory bowel disease found that ex vivo IL-12 stimulation led to IFN-γ production in Th17 cells that were isolated as CCR6+CXCR3− cells from mesenteric lymph nodes." (PMID 32774332, 2020). "In the guts of inflammatory bowel disease (IBD) models, CCR6 deficiency indicated pronounced changes in the overall histology at the Peyer’s patches." (PMID 30453514, 2018). "CCR6 is also associated with inflammatory bowel disease (IBD)." (PMID 26870082, 2016). "The chemokine CCL20 and its receptor CCR6 are putative drug targets in inflammatory bowel disease, and CCL20 is a novel IBD predilection gene." (PMID 26536229, 2015). "Reduction of CCR6 and CXCR3 in SIP T cells is in contrast to increased expression of these migration chemokines that has been reported in inflammatory bowel disease." (PMID 36825028, 2023). "CCL20 can be induced by pro-inflammatory signals such as TNF-α or TLR, bind CCR6 and induce the recruitment of B cells with high CCL6 expression into intestinal epithelial cells of patients with inflammatory bowel disease in response to inflammatory stimuli." (PMID 36419192, 2022). "Among DP8α T cells, there were F. prau-specific T cells co-expressing CCR6 and CXCR6, decreased in inflammatory bowel disease (IBD) patients." (PMID 32099648, 2020).
Arthritis (19 papers, 2010 to 2023). Inflammation of a joint. "Our study demonstrated that γδ T cells were not important for the progression of arthritis, however their contribution to the generation of pathogenic CD4+CCR6+ T cells during arthritis cannot be excluded." (PMID 31778214, 2020). "In this study, we therefore studied the effect of CCR6 deficiency in three different models of experimental arthritis, each with distinct, non‐overlapping pathomechanisms." (PMID 30133119, 2018). "Previous studies have also shown a significant reduction in arthritis severity and migration of Th17 cells to joints following the use of monoclonal antibodies against CCR6." (PMID 37697373, 2023). "CCR4, CCR6, CCR7, CCR9, CXCR5, and CXCR6 deficiency ameliorated arthritis in CIA mice by suppressing the migration of Th17 cells (CCR4), DC (CCR7), and CD11b+ splenocytes (CCR9)." (PMID 36860872, 2023). "Our data suggest that all CCR6+ memTh subpopulations can activate SF, although there are differences between the subpopulations and between healthy individuals and patients with arthritis." (PMID 34082814, 2021). "In conclusion, our study demonstrates that IL‐23R+ CD4+CCR6+ T cells are present in the inflamed joints during the early stages of arthritis." (PMID 31778214, 2020). "The receptors and their ligand CXCL13 and CCL20 have been suggested to be important for B-cell migration into the inflamed synovium in human arthritis, and CCR6 has been reported to be increased in peripheral B cells from arthritis patients." (PMID 31882654, 2019). "CCR6+ ILC3s from mice with arthritis expressed significantly higher levels of IL-17A and IL-22 mRNA than did comparable cells from control mice (p < 0.0001 and p = 0.015)." (PMID 31470891, 2019). "Our findings are in line with previous reports which describe a role of CCR6 in the SKG arthritis model." (PMID 30133119, 2018). "In this study, we investigated the role of CCR6 in the pathogenesis of arthritis using three different murine arthritis models." (PMID 30133119, 2018). "To address the role of CCR6 in arthritis, we first analysed WT and CCR6−/− mice in the collagen‐induced arthritis (CIA) model." (PMID 30133119, 2018). "To decipher the exact role of CCR6, we therefore analysed CCR6−/− mice in three different arthritis models." (PMID 30133119, 2018). "In sharp contrast, CCR6−/− mice developed a less severe arthritis in the CIA mouse model, which is dependent on the adaptive immune system." (PMID 30133119, 2018). "The interaction between CCR6 and CCL20 plays an important role in the migration of pathogenic Th17 cells in arthritis, and a majority of Th17 cells express CCR6." (PMID 25888974, 2015). "Inhibition of ccr6, by monoclonal antibodies in mice, has been reported to supress arthritis." (PMID 34867944, 2021). "Furthermore, IL‐23R(GFP)+CD4+CCR6+ T cells are present at the site of inflammation during the early phases of arthritis." (PMID 31778214, 2020). "Since we detected both IL‐23R(GFP)+ γδ T cells and IL‐23R(GFP)+CD4+CCR6+ T cells in the inflamed joints of mice, we aimed to investigate which of these cells are important for the progression of IL‐23R‐dependent arthritis." (PMID 31778214, 2020). "We therefore induced the K/BxN serum transfer arthritis in WT and CCR6−/− mice." (PMID 30133119, 2018). "Administration of anti‐CCR6 antibody suppressed the severity and onset of arthritis." (PMID 30133119, 2018). "Both hTNFtg and hTNFtg/CCR6−/− mice did develop clinical signs of arthritis." (PMID 30133119, 2018). "Furthermore, we showed that CCR6, which is important for the development of arthritis in SKG mice by enhancing the migration of Th17 cells, was expressed normally in Cxcr4-deficient T cells." (PMID 20939892, 2010). "Interestingly, while γδ T cells did not affect the disease severity, WT CD4+CCR6+ T cells were able to induce arthritis in IL‐23R deficient mice." (PMID 31778214, 2020). "The role of CCR6 in the development of arthritis so far remains unclear." (PMID 30133119, 2018).
Arthritis (continued). "In addition, we could also dissect the role of CCR6 in innate immunity‐driven models of arthritis (hTNFtg and K/BxN serum transfer arthritis), as compared to the CIA model of arthritis that depends on the adaptive immune system." (PMID 30133119, 2018). "SLE patients revealed low SLEDAI score, less myositis, fever, alopecia, vasculitis, arthritis, oral ulcer, and decreased number of CXCR5+PD-1+CCR7lo Tfh cells, CCR6+CXCR3-CCR4+CCR7lo Th17 cells." (PMID 38164134, 2023). "During the early phases of arthritis, IL‐23R+CD4+CCR6+ T cells were increased in the pLNs of mice and were present in the joints, while IL‐23R+ γδ T cells were not present in the joints at this time point." (PMID 31778214, 2020). "Mice treated with acarbose prior to arthritis induction had significantly increased CD4+CD25+Foxp3+ Treg cells as well as elevation of Helios and CCR6 as demonstrated in both percentage and absolute Treg cell numbers." (PMID 32116681, 2019). "This approach allowed us to study the role of CCR6 in spontaneous (hTNFtg) and induced (CIA and K/BxN serum transfer arthritis) models of arthritis." (PMID 30133119, 2018). "Migration of Th17 cells to the joints in arthritis is orchestrated mainly by CCL20 and corresponding receptor CCR6 expressed on Th17 cells." (PMID 25888974, 2015). "Flow cytometry analysis showed significantly increased recruitment of CD45+CD4+Ccr6+ (Th17) cells and CD45+CD4–Ccr6+ (expected as a B cell–rich fraction) cells in arthritis tissue from Uhrf1ΔCol6a1 mice in the late but not early phase of STA." (PMID 35472067, 2022). "In this context, CD4+CCR6+ T cells, but not γδ T cells, are crucial for the progressive phase of arthritis." (PMID 31778214, 2020). "Whereas, neither CD4+CD25+Foxp3+Helios+ nor CCR6+ response to α-glucosidase inhibitors was observed in the groups when treatment started at arthritis induction." (PMID 32116681, 2019). "Furthermore, CD4+CCR6+ T cells, but not γδ T cells, are important for IL‐23R‐dependent progression of arthritis." (PMID 31778214, 2020). "Finally, adoptive transfer experiments revealed that CD4+CCR6+ T cells and not γδ T cells drive arthritis progression." (PMID 31778214, 2020). "Also, in the spleen and inguinal LNs, which drain from the site of immunization, the percentage of IL‐23R(GFP) expressing CD4+CCR6+ T cells was increased during arthritis compared to naïve condition (data not shown)." (PMID 31778214, 2020). "On the other hand, whether CCR6 plays a role in the adaptive or the innate immune system for the development of arthritis has not been analysed so far." (PMID 30133119, 2018). "Based on CXCR5 and CCR6 internalization and B-cell migration experiments, our results suggest that CXCL13 and CCL20, the respective ligands of CXCR5 and CCR6, by acting synergistically, might participate in the recruitment of B cells in the synovium in patients with arthritis." (PMID 29880013, 2018). "During early arthritis, IL‐23R(GFP)+CD4+CCR6+ T cells, but not IL‐23R(GFP)+ γδ T cells, were present in the inflamed joints." (PMID 31778214, 2020).
colon carcinoma (19 papers, 2008 to 2025). "For example, chemokine receptor-modified T-cells (e.g., CCR4- and CCR6-engineered variants) selectively home to tumor-draining lymph nodes and intratumoral regions in murine colon cancer models, markedly improving therapeutic efficacy." (PMID 40746833, 2025). "Furthermore, it has been observed that an antibody targeting CCR6 inhibits the growth of syngeneic mouse colon cancers in a CCR6-deficient mouse model where CCR6 expression is thus confined exclusively to the transplanted tumor." (PMID 34853656, 2021). "A study that assessed the CCR6 expression in colon cancer detected CCR6 expression in samples from colon cancer patients for the first time and revealed its higher expression in colon cancer relative to normal controls." (PMID 36375474, 2022). "It has been found that colon cancer cells recruit monocytes to infiltrate tumor tissues by secreting CCL20 to bind with the monocyte receptor CCR6 in mouse model of colon cancer." (PMID 33224886, 2020). "CCR6 signaling also promotes murine transplantable colon cancer by recruiting macrophages to the TME through a CCL2-CCR6 axis, which results in the release of IL-1β, IL-6, and TNFα, further enhancing tumor progression." (PMID 32733461, 2020). "For these experiments we employed HCT116 cells, a human colon cancer line that expresses CCR6 at a high level and is easily transfectable." (PMID 27626929, 2016). "In the present study, CCR6 expression was observed to be more frequent in UCAC compared with sporadic colon cancer." (PMID 24179507, 2013). "CC-chemokine ligand 20 (CCL20) and its selective receptor CCR6, known to be responsible for the chemoattraction of TAMs in homeostatic conditions, have been recently found to be involved in metastatic progression of colon cancer." (PMID 36045408, 2022). "Actually, CCR6 is most highly expressed in metastatic colon cancer cells." (PMID 36375474, 2022). "Instead, in the MC38 colon carcinoma model, anti-tumoral efficacy as well as lymph node vs. tumor-homing patterns were mostly driven by CCR4 and CCR6, respectively." (PMID 37301772, 2023). "C1 (Tumor-Treg) showed 112 DEGs between colon cancer and rectal cancer, such as TNF and CXCR3, which were up-regulated, while CXCR6 and CCR6 were down-regulated in colon cancer in comparison to that of rectal cancer." (PMID 33584715, 2020). "Circulating MAIT cells exhibited high levels of CCR6 and CXCR6, and their corresponding chemokines, such as CCL20 and CXCL16, were strongly expressed in colon cancer tissues." (PMID 27517754, 2016). "Next, the expression of the two markers, CCL20 and CCR6, were compared in UCAC and sporadic colon cancer." (PMID 24179507, 2013). "Interestingly, CCL20 secreting TAMs were induced via IL-6-regulated macrophage polarization in a mouse model of colon cancer; in which, CCL20 promoted cancer progression by recruiting CCR6+ lymphocytes." (PMID 34439098, 2021).